ALCAM (activated leukocyte cell adhesion molecule)
Diseases named in the same sentence as ALCAM in open-access papers (continued):
Sharing a sentence is not in itself a finding about the gene and the disease.
melanoma (continued). "At the same time they observed that in melanomas and metastatic foci ALCAM immunoreactivity was most intense." (PMID 26134500, 2015). "The study using melanoma cell lines showed that overexpression of ALCAM is directly related with the increase of cytoaggregation and the ability to form cell nests." (PMID 26134500, 2015). "As regards Breslow thickness it was shown that over 70 % of over 1.5 mm thick melanomas had increased ALCAM expression in cancer cells." (PMID 26134500, 2015). "Paradoxically, an opposite situation occurs in the case of ALCAM adhesion protein, where it is the upregulation and increase of homophilic interactions is strongly correlated with melanoma progression (ALCAM paradox)." (PMID 26134500, 2015). "Our study is the first one to evaluate the effect of increased ALCAM expression on long-term survival in melanoma patients." (PMID 26134500, 2015). "The MTFs also expressed ALCAM (Gene ID#214), a marker which is characteristically expressed in melanomas." (PMID 26267609, 2015). "MTFs stained strongly for markers specific for melanocyte lineage, including MLANA, and for cell surface markers often found in melanomas, such as ALCAM." (PMID 26267609, 2015). "Other cytophysiological analyses revealed the existence of functional homotypic interactions of the ALCAM-ALCAM type which were identified in CD6-negative melanoma cell lines." (PMID 26134500, 2015). "A review of world literature (PubMed; 1970–2014; key words: ALCAM, malignant melanoma) identified only 2 reports that were concerned with analysis of ALCAM expression in tissue material obtained from cutaneous melanoma patients using immunohistochemistry." (PMID 26134500, 2015). "ALCAM (activated leukocyte cell adhesion molecule, CD166, MEMD) is a transmembrane protein of immunoglobulin superfamily (Ig-SF) and plays an important role in human malignant melanoma progression and formation of locoregional and distant metastases." (PMID 26134500, 2015). "For example, an increase in ALCAM expression is found in higher-stage more aggressive malignant melanoma." (PMID 23024593, 2012). "Regarding melanoma, ALCAM mRNA was markedly elevated in most of the cell lines (LOX, C8161.9, MelJuso) in agreement with the increased expression in primary tumors." (PMID 20929568, 2010). "Our data in melanoma cells is consistent with previous reports showing that transformation of avian lymphoma B-cells with v-rel induces ectopic expression of ALCAM." (PMID 20929568, 2010). "Given the marked elevation of expression of ALCAM in vertically growing primary melanoma tumors, it is likely that the ALCAM gene locus is a downstream target of NF-κB in melanoma." (PMID 20929568, 2010). "Over-expression of p65 NF-κB increased ALCAM promoter activity, while p65 occupied the cognate motif on the endogenous ALCAM promoter in melanoma cells lines." (PMID 20929568, 2010). "Moreover, melanoma cells express adherent molecules, such as N-cadherin, integrin α4β1, and ALCAM, which allow melanoma cells to attach to TECs, further promoting invasion and metastasis." (PMID 38893071, 2024). "In melanoma, miR-214 has also been shown to upregulate ALCAM expression." (PMID 34680335, 2021). "Over-expression of ALCAM increased melanoma cell aggregation and metastasis." (PMID 34207884, 2021). "Similarly, EVs derived from the PDAC and melanoma cell lines included proteins (e.g., ALCAM and galectin-3, respectively) previously reported to be up-regulated in the serum of patients with PDAC and melanoma, respectively." (PMID 32886718, 2020). "Moreover, in a metastatic melanoma cell line, interfering with endogenous ALCAM through the expression of an amino-terminally truncated ALCAM, which disrupts ALCAM–ALCAM interactions, increases cell invasive growth in skin reconstructions." (PMID 33270750, 2020). "ALCAM expression correlates with melanoma progression, as it is much more abundant in late stages." (PMID 31324051, 2019).
melanoma (continued). "Interestingly, multivariable Cox analysis revealed the effect of high percentage of ALCAM-positive melanoma cells from the primary tumor as a potential, independent prognostic factor, yet without statistical significance." (PMID 26134500, 2015). "The involvement of ALCAM in melanoma progression should be seen as composed of two stages." (PMID 26134500, 2015). "Furthermore, the results were similar for a high percentage (>75 %) of ALCAM-positive melanoma cells in primary tumor (P = 0.007 and P = 0.025 for CSOS and DFS, respectively)." (PMID 26134500, 2015). "In spite of large scale multicenter research on cytobiochemistry and oncobiology of ALCAM, numerous questions remain that if answered could help to develop new, promising treatment options and implement a more personalized treatment of melanoma patients." (PMID 26134500, 2015). "Interestingly, statistical analysis showed that higher percentage of ALCAM-positive melanoma cells is closely related with decreased intensity of lymphocytic inflammatory infiltration (P = 0.01)." (PMID 26134500, 2015). "Additionally lower ALCAM immunoreactivity in nodal metastatic foci was significantly statistically correlated with deeper melanoma invasion in the primary tumor according to Clark scale (P = 0.032)." (PMID 26134500, 2015). "High ALCAM expression in melanoma cells of the primary tumor can be used as a marker of negative outcome and may indicate a more invasive phenotype of cancer cells, which would require a more intensive therapeutic strategy." (PMID 26134500, 2015). "It evaluates ALCAM reactivity in 71 benign melanocytic lesions, 71 melanomas and 84 metastases." (PMID 26134500, 2015). "A similarly high degree of methylation was found in the FEMX-1 melanoma cell line (up to 75% of specific CpG residues), which also lacks ALCAM expression while all other tumor cells with appreciable ALCAM expression had a negligible (0-5%) level of DNA methylation." (PMID 20929568, 2010). "By RT-PCR only the activated leukocyte cell adhesion molecule CD166 and the B cell specific Moloney murine leukaemia virus integration site BMI-1 both involved in melanoma metastasis were detected in all analyzed melanoma cell lines." (PMID 22275987, 2008). "Consequently, ALCAM promoted malignant melanoma progression." (PMID 34943783, 2021). "It must be stressed that it is a hypothesis that needs to be supplemented and validated empirically with a much larger study group and animal models of metastasis, however, it is a voice in the discussion and confirms the hypotheses concerning the role of ALCAM in melanoma progression." (PMID 26134500, 2015). "Similarly, IgSF members such as L1CAM (CD171), NCAM (CD56), PECAM-1 (CD31), ALCAM (CD166), and ICAM-1 (CD54) have been associated with metastatic progression in a range of cancers including melanoma, glioma, breast, ovarian, endometrial, prostate, and colon cancer." (PMID 22272201, 2012). "SSSRs encompass Extracellular Matrix Metalloproteinase Inducer (EMMPRIN), Activated Leukocyte Cell Adhesion Molecule (ALCAM), Toll-like Receptor 4 (TLR-4), Neuroplastin (NPTN) β, and Melanoma Cells Adhesion Molecule (MCAM)." (PMID 33256110, 2020). "Further studies showed that the anti-GD2 Ab 14G2a cross-reacts with a 105 kDa glycoprotein expressed by murine and human neuroblastoma and melanoma cells, identified as activated leukocyte cell adhesion molecule (ALCAM/CD166)." (PMID 32075083, 2020). "MTFs were readily identifiable in primary melanomas, with strong staining for melanocyte (MLANA and ALCAM), macrophage (CD204, CD206), and epithelial (pan-KRT, EpCAM) markers." (PMID 26267609, 2015). "Similar reports have indicated that upregulation of ALCAM and L1CAM mediates homophilic cell-cell cohesion in invading melanoma and colorectal carcinoma, respectively." (PMID 22272201, 2012).
melanoma (continued). "The reduction in invasiveness we observe appears at odds with the finding that amino-truncated ALCAM expression served to disrupt ALCAM junctions and to reduce MMP-2 activation, but actually increased the invasive capacity of BLM cutaneous melanoma cells." (PMID 22745734, 2012). "Interestingly, no ALCAM immunoreactivity was observed in any of the early stage melanomas (Clark I and II)." (PMID 26134500, 2015).
colorectal cancer (51 papers, 2008 to 2025). A primary or metastatic malignant neoplasm that affects the colon or rectum. "This meta-analysis revealed that high levels of ALCAM in colorectal cancer are associated with poor overall survival, nodal status, tumour grade, and distant metastasis." (PMID 34680335, 2021). "Activated leukocyte cell adhesion molecule (ALCAM) has been linked to the development and progress of colorectal cancer (CRC)." (PMID 28537909, 2017). "However, only four studies on colorectal cancer (CRC) were enrolled to evaluate the association between ALCAM overexpression and clinical features." (PMID 28537909, 2017). "Research has demonstrated that SOSTDC1 plays a role in promoting invasion of colorectal cancer and liver metastasis by interacting with ALCAM/CD16635." (PMID 38012244, 2023). "A meta-analysis demonstrated that high levels of ALCAM was correlated with shorter overall survival and the appearance of distant metastases in colorectal cancer." (PMID 36614319, 2023). "Recent studies reported that high tissue expressions of ALCAM are correlated with poor survival in pancreatic, bladder and colorectal cancer." (PMID 35689436, 2022). "It has also been shown that ALCAM, together with a few other cell cycle and drug markers, are key markers in resistance colorectal cancer cells (HCT116 and HT29) to chemotherapy drugs and can also be altered in response to capsaicin in bladder cancer cells." (PMID 34680335, 2021). "For example, membranous ALCAM expression and ALCAM overexpression are independent markers of poor prognosis in colorectal carcinoma and pancreatic cancer, respectively." (PMID 33270750, 2020). "In colorectal cancer, analysis of cytoplasmic and membranous ALCAM expression indicated a significant correlation between membranous ALCAM expression and reduced patient survival rates." (PMID 31695844, 2019). "We previously demonstrated in colorectal cancer that reduced detection of the ALCAM extracellular domain in tumor tissue is due to ALCAM shedding which, in turn, corresponds with poor patient outcome." (PMID 27894096, 2017). "A study of colorectal cancer demonstrated overexpression of ALCAM neoplastic regions compared to normal surrounding tissue; membranous ALCAM staining correlated with reduced patient survival." (PMID 22745734, 2012). "There have been some extensive studies on the role of ALCAM in colorectal cancer." (PMID 34680335, 2021). "Thus, it is plausible that ALCAM is an indicator of poor clinical outcomes of patients with colorectal cancer." (PMID 34680335, 2021). "Its expression inversely correlates with “activated leukocyte cell adhesion molecule” (ALCAM/CD166), a stem cell marker that is present at the crypt base and on highly tumorigenic human colorectal cancer (CRC) cells." (PMID 41118768, 2025). "Transcriptomic profiling of oxaliplatin-resistant colorectal cancer (CRC) cells derived from DLD1 and HCT116 identified ALCAM activation with concurrent CD22, CASP1, and CISH suppression as key molecular features of oxaliplatin non-response." (PMID 41009436, 2025). "CREB crosstalks with KRAS to promote colon carcinogenesis and positively regulates ALCAM (CD166) and PROM1 (CD133) expression, thus promoting colorectal cancer stemness and metastasis." (PMID 38233872, 2024). "This view has been challenged by a recent in vitro study with human colorectal cancer cells (CRC), in which both CD166/ALCAM and CD318/CDCP1 are highly expressed." (PMID 38139340, 2023). "For example, ALCAM/CD166 mediates the docking and uptake of cancer cell derived EVs and promotes the peritoneal metastasis cascade in colorectal cancer and ovarian cancer." (PMID 35954383, 2022). "Bartolomé and colleagues have recently reported that ALCAM, via its interaction with SOSTDC1 (sclerostin domain containing-1), increases the hepatic metastases from colorectal cancer." (PMID 34680335, 2021).
colon carcinoma (40 papers, 2009 to 2025). "Recently, a study using an oxaliplatin resistance-related gene signature (consisting of CD22, CASP1, CISH, and ALCAM) to predict the survival of patients with colon cancer found that this gene signature has a better predictive value." (PMID 36145360, 2022). "Thereafter, we established a prognosis signature based on four genes [CD22, CASP1, CISH, and activated leukocyte cell adhesion molecule (ALCAM)] to evaluate the prognosis for colon cancer patients." (PMID 34026619, 2021). "Afterward, we established a model to predict the prognosis of colon cancer using four oxaliplatin resistance-related genes (ALCAM, CD22, CASP1, and CISH) on the basis of stepwise regression and LASSO Cox regression." (PMID 34026619, 2021). "In several KRAS mutated cancers, the CD44 molecule associates with ALCAM/CD166 promoting an aggressive phenotype that predicts worse outcome and increased risk of liver and lung metastasis (e.g., colon cancer)." (PMID 31552188, 2019). "We recently found variants in cancer stem cell genes (CD44, ALCAM and LGR5) significantly associated with increased time to recurrence (TTR) in patients with stage III and high-risk stage II colon cancer treated with 5-fluorouracil (5-FU)-based chemotherapy." (PMID 25665511, 2015). "In the present study, we aimed to validate the single biomarkers CD44 rs8193 C>T, ALCAM rs1157 G>A and LGR5 rs17109924 T>C based on our preliminary findings in a large and independent study cohort of 742 stage II and III colon cancer patients." (PMID 25665511, 2015). "The design of CAR-T cells with CD6 as a chimeric receptor has shown cytotoxic effects on ALCAM+ but not CD318+ human colon cancer cell lines." (PMID 40391211, 2025). "The risk scores calculated based on the expression levels and coefficients of four mRNAs (ALCAM, CD22, CASP1, and CISH) might be used to precisely and independently predict the prognosis of colon cancer." (PMID 34026619, 2021).
prostate carcinoma (34 papers, 2010 to 2025). A carcinoma that arises from epithelial cells of the prostate gland. "Serum levels of ALCAM have shown promise as a prognostic indicator in prostate cancer, while increased tissue levels of ALCAM have been associated with a more aggressive cellular phenotype and metastasis." (PMID 37705744, 2023). "Taken together, ALCAM appears to be a promising biomarker for prostate cancer progression, with enhanced serum expression associated with poorer prognosis." (PMID 31695844, 2019). "In a bioinformatic analysis, ALCAM has been integrated in the cellular senescence-related gene prognostic index to predict metastasis and radioresistance in prostate cancer." (PMID 37705744, 2023). "One previous study has highlighted the potential of ALCAM as a biomarker for prostate cancer progression." (PMID 37705744, 2023). "In patients with prostate cancer, those with metastasis, with nodal positive tumours, and, in particular, those who died of prostate cancer had significantly higher levels of circulating ALCAM." (PMID 34680335, 2021). "In a large cohort of tissue microarray (n = 2390), ALCAM was found largely membranous stained in prostate cancers (69.9%)." (PMID 34680335, 2021). "The Yegnasubramanian Prostate Cancer gene set is positively correlated with ALCAM and TMPRSS2 gene expression." (PMID 32899474, 2020). "Our study demonstrates the significance of serum ALCAM as a potential marker of prostate cancer progression, highlighting its use as a possible indicator of poor prognosis." (PMID 31695844, 2019). "The impact of an ALCAM-Fc chimera, containing Trp28-Ala526 of ALCAM, on prostate cancer cell attachment to HECV endothelial cells was explored." (PMID 31695844, 2019). "The current study aims to further assess the importance of ALCAM in prostate cancer and the prognostic potential of serum ALCAM as a biomarker for prostate cancer progression." (PMID 31695844, 2019). "ALCAM transcript expression was screened in a number of human prostate, prostate cancer, osteoblast (hFOB1.19) and endothelial (HECV) cell lines." (PMID 31695844, 2019). "Currently, there is very little information regarding the clinical relevance of serum ALCAM as a prognostic factor for prostate cancer progression." (PMID 31695844, 2019). "Further work on larger cohorts of prostate cancer patients are needed to further realize the potential of serum ALCAM, potentially in conjunction with other markers, as a biomarker for prostate cancer and disease progression." (PMID 31695844, 2019). "ALCAM can also function as the therapeutic target using anti-ALCAM monoclonal antibody, conjugated to the nanoparticles to eliminate prostate cancer and OS cells." (PMID 30995926, 2019). "When other cancer types are considered, the picture becomes murkier – one study by Kristiansen and colleagues found that ALCAM protein expression is high in low-grade prostate cancer, and is lost in higher-grade tumors." (PMID 22745734, 2012). "As seen in prostate cancer cells, ALCAM-targeted nanoparticles were rapidly internalized by osteosarcoma cells suggesting a strategy for intracellular delivery of anticancer agents." (PMID 23024593, 2012). "First, a report by Tomita and colleagues described the coordinate recruitment of epithelial (E)-cadherin and ALCAM to cell contacts upon transfection of alpha-catenin into prostate cancer cell lines that have lost this protein." (PMID 22745734, 2012). "However, in breast, thyroid and prostate cancers, a high-expression level of ALCAM was a favorable prognostic factor." (PMID 40118855, 2025). "In addition to the marker, ALCAM is also a functional regulator of prostate cancer progression in response to TGF-β signaling." (PMID 37705744, 2023). "In prostate cancer, the highest ALCAM expressions were found in metastatic cases." (PMID 35689436, 2022). "A number of studies have explored the impact of ALCAM expression in prostate cancer." (PMID 34680335, 2021).